SQOR (sulfide quinone oxidoreductase)
Diseases named in the same sentence as SQOR in open-access papers (continued):
Sharing a sentence is not in itself a finding about the gene and the disease.
heart failure (1 paper, 2025). Inability of the heart to pump blood at an adequate rate to meet tissue metabolic requirements. "The successful development of the first highly selective SQOR inhibitors demonstrates that SQOR is indeed a “druggable” target, opening a new paradigm for treating diseases like heart failure." (PMID 41210256, 2025).
inflammatory bowel disease (1 paper, 2025). A spectrum of small and large bowel inflammatory diseases of unknown etiology. "SQOR also plays an important role in inflammatory bowel disease (IBD)." (PMID 41210256, 2025).
intracerebral hemorrhage (1 paper, 2025). A cerebrovascular disorder characterized by bleeding into one or both cerebral hemispheres including the basal ganglia and the cerebral cortex. "Deletion of SQOR abolishes therapeutic benefits of H2S following intracerebral hemorrhage by targeting mitochondrial electron transport chain function to induce mitochondrial uncoupling." (PMID 40661137, 2025).
ischemic heart disease (1 paper, 2024). "We also show that sulfide-quinone oxidoreductase (SQOR) participates in plasma-irradiated Cys-induced cardioprotection against I/R injury by preserving supersulfide metabolism, suggesting a potential therapeutic strategy for ischemic heart disease." (PMID 39637599, 2024).
lung adenocarcinoma (1 paper, 2025). A carcinoma that arises from the lung and is characterized by the presence of malignant glandular epithelial cells. "The effect of SQOR in pan-cancer on the prognosis of tumor patients was further explored, and the results showed that SQOR was a prognostic risk factor in PDAC, liver hepatocellular carcinoma, brain lower grade glioma, lung adenocarcinoma, and uveal melanoma (UVM)." (PMID 40375994, 2025).
tumor (7 papers, 2021 to 2025). "SQOR was upregulated in tumor tissues and positively associated with both hypoxia score and ferroptosis resistance." (PMID 40375994, 2025). "As our above studies have shown that high levels of hypoxia and SQOR are present in tumor cells and differential analysis indicates alterations in the ferroptosis pathway in tumor cells." (PMID 40375994, 2025). "Bulk RNA sequencing and single-cell transcriptomics analyses consistently demonstrated significant SQOR upregulation in tumor and normal pancreatic tissues/cells." (PMID 40375994, 2025). "Accordingly, SQOR is an attractive therapeutic target, yet its modulation should be precisely matched to tumor metabolic and immune contexts; rigorous clinical investigation remains essential." (PMID 41210256, 2025). "This stark contrast depends on the tumor’s metabolic demands and immune microenvironment, indicating that SQOR’s role is highly context-dependent." (PMID 41210256, 2025). "Analysis of SQOR expression levels in normal and tumor tissues of the pancreas revealed that SQOR was upregulated in tumor tissues and was significantly different from normal tissues (p<0.05)." (PMID 40375994, 2025). "SQOR promotes the malignant progression of PDAC in hypoxic environment by enhancing the resistance of tumor cells to ferroptosis." (PMID 40375994, 2025). "In cancer, SQOR expression levels vary across different stages and tumor types, influencing tumor growth and survival by regulating H2S metabolism and cellular sensitivity to ferroptosis." (PMID 41210256, 2025). "The results demonstrated that SQOR exhibited a tumor-suppressive function, whereas SFXN4 facilitated tumor growth." (PMID 39569192, 2024). "Furthermore, SQOR inhibitor in combination with ferroptosis inducer has the potential to inhibit tumor growth in vivo in a synergistic manner." (PMID 40375994, 2025). "Knockdown of SQOR enhanced tumor growth, whereas knockdown of SFXN4 yielded an opposing effect." (PMID 39569192, 2024). "Therefore, SQOR’s influence on ferroptosis in cancer depends on tumor metabolic demands and the immune microenvironment: it may help tumor cells survive by preventing ferroptosis, or alternatively enhance anti-tumor immunity by permitting some oxidative damage." (PMID 41210256, 2025). "As a result, helping expression induction or activation of ETHE1 and SQOR proteins will increase sulfide scavenging and this would hinder CRC tumor growth." (PMID 34249670, 2021). "In vivo experiments demonstrated that both the SQOR inhibitor HTS07545 and the ferroptosis inducer erastin could inhibit tumors and both have synergistic inhibitory effects on tumor growth with fewer side effects." (PMID 40375994, 2025). "Finally, the specific molecular mechanisms by which SQOR and SFXN4 affect the tumor microenvironment and immunotherapeutic response need to be further investigated." (PMID 39569192, 2024). "Hence, we hypothesized that SQOR may activate the interaction network between NK T cells and Gamma belta T cells, thereby increasing the abundance of immune cell infiltration, altering the tumor microenvironment, and enhancing the patient’s response to immunotherapy." (PMID 39569192, 2024).
cancer (4 papers, 2021 to 2025). A tumor composed of atypical neoplastic, often pleomorphic cells that invade other tissues. "This review provides a systematic overview of the core biological functions of SQOR in H2S metabolism and explores recent research advances across diseases of the cancer, cardiovascular, nervous, and reproductive systems." (PMID 41210256, 2025). "This suggests that SQOR under hypoxic conditions may affect cancer progression by modulating the ferroptosis pathway." (PMID 40375994, 2025). "Notably, SQOR’s protective effect against ferroptosis is also evident outside of cancer." (PMID 41210256, 2025).
cardiovascular disease (1 paper, 2025). "Thus, SQOR has a dual role in cardiovascular disease and can exert opposite effects under different pathological conditions." (PMID 41210256, 2025).
neurodegenerative disease (1 paper, 2025). A disorder of the central nervous system characterized by gradual and progressive loss of neural tissue and neurologic function. "Numerous studies have shown that a common pathological feature in many neurodegenerative diseases is reduced SQOR expression." (PMID 41210256, 2025).
SQOR also shares sentences with these, for which no sentence is quoted: colon cancer (2 papers); Encephalopathy (2); ulcerative colitis (2); aortic valve stenosis (1); atherosclerosis (1); ethylmalonic encephalopathy (1); gastrointestinal infections (1); hepatitis B (1); hepatitis C (1); infection (1); measles (1); medulloblastoma (1); metabolic disease (1); Mitochondrial encephalopathy (1); Mitochondrial myopathy (1); myocardial hypertrophy (1); myocardial ischemia (1); nephrotic syndrome (1); neuroblastoma (1); Obesity (1); oral cancer (1); osteonecrosis (1); periodontitis (1); postmenopausal osteoporosis (1); rectal cancer (1); renal failure (1); Sepsis (1); Tremor (1); ulcers (1); uveal melanoma (1).